GSK3B (glycogen synthase kinase 3 beta)
Diseases named in the same sentence as GSK3B in open-access papers (continued):
Sharing a sentence is not in itself a finding about the gene and the disease.
cancer (continued). "Impediment of Thr-628 phosphorylation attenuates the stimulatory effects of LCRMP-1 on filopodia forming, migration and invasion abilities in cancer cells; simultaneously, kinase-dead GSK3β diminishes regulation of LCRMP-1 on cancer cell invasion." (PMID 22363707, 2012). "Frequent activation of Akt signaling pathway has been reported in many human cancers, and GSK-3β has been identified as one of the Akt's molecular targets." (PMID 22470469, 2012). "Collectively, these results demonstrate that GSK3β-dependent phosphorylation of LCRMP-1 provides an important mechanism for regulation of LCRMP-1 on cancer cell invasiveness and clinical outcome." (PMID 22363707, 2012). "In our present study, we provide novel evidence that UVC inhibits cancer cell migration by suppressing the Akt-GSK-3β pathway." (PMID 22200892, 2012). "Positive regulators of GSK-3β are often utilized for enhancing the proapoptotic effects of GSK-3β in the context of chemotherapy for cancer treatment." (PMID 22675363, 2012). "The interplay between GSK-3β regulation and other cell death stimuli is being carefully studied across a wide variety of cancer types, and there is promising data suggesting a strong role for this form of therapy in the near future." (PMID 22675363, 2012). "Accordingly, investigating the functions and pathologic roles of GSK3β should establish a firm molecular basis for future cancer treatments that target this kinase." (PMID 24212624, 2011). "Although the putative role of GSK3β in cancer is still debated, the overall results indicate that aberrant expression and activity of GSK3β is likely to be a common and fundamental characteristic of a broad spectrum of cancers." (PMID 24212624, 2011). "This led us to propose GSK3β as a potential target for cancer treatment and to apply for domestic and international patents." (PMID 24212624, 2011). "The function of GSK-3β in human cancer cells has been most frequently evaluated in in vitro studies, which reported opposing roles of GSK-3β." (PMID 20704706, 2010). "There have been a number of conflicting reports concerning the prognostic implication of activated GSK-3β in human cancers." (PMID 20704706, 2010). "The inactivation of GSK3β has been reported in most cancers of epithelial origin, such as skin, breast, and in cancers of the oral cavity, salivary glands, larynx, and esophagus." (PMID 20537194, 2010). "In other studies, GSK3β was shown to promote cancer cell migration by cooperating with h-prune, or with small GTPase Rac." (PMID 20637111, 2010). "Although both GSK-3β and cyclin D1 are known to be involved in cell cycle regulation, their relationship in cancer cells remains controversial." (PMID 20704706, 2010). "There was also a concomitant decrease (2.5 fold) in mRNA transcript of CTNNB1 and other elements of Wnt/β-catenin signaling (e.g. axin, DVL1, GSK3β) in cancer cells compared to normal cells." (PMID 20454608, 2010). "As a result, the cancer cells upregulate the survival machinery through activation of survival pathways such as Akt/GSK3β/Wnt signaling at low doses of resveratrol." (PMID 20504360, 2010). "GSK-3β has recently been shown to be a crucial enzymatic regulator of cancer cell survival in human tumorigenesis." (PMID 21110852, 2010). "This study is designed mainly to determine if β-catenin is a target of MSeA in CRC, HNSCC and CaP cancers; and to evaluate the role of GSK-3β in the degradation of β-catenin and if such an effect is associated with enhanced cytotoxicity of anticancer drugs." (PMID 21126356, 2010). "GSK-3β has been shown as positive regulator of NF-κB-mediated survival and proliferation of cancer cells." (PMID 19920820, 2009). "Previous studies suggest a positive role for GSK-3β in the regulation of NF-κB-mediated cancer cell survival." (PMID 19920820, 2009). "Our objectives were to determine the expression pattern of GSK-3β and to assess the anti-cancer effect of GSK-3β inhibition in RCC." (PMID 19920820, 2009).
cancer (continued). "Although inactive form of GSK-3β is able to translocate to the nucleus from cytoplasm, it is rapidly degraded by proteasomal pathway within the nucleus of the cancer cell." (PMID 19920820, 2009). "BIO, GSK3β-specific siRNA, and genetic agonists of Wnt signalling all suppressed hTERT promoter activity in five cancer cell lines." (PMID 19649288, 2009). "Further studies on the expression profiles of pGSK3β and pAkt, using phospho-specific antibodies will certainly help in elucidating the role of GSK3β regulation in Invasive ductal carcinomas of breast." (PMID 19751508, 2009). "Inhibition of GSK3β in human cancer cells results in centrosome dysregulation and abnormal mitosis." (PMID 40152591, 2025). "Furthermore, inhibiting GSK3β has been shown to enhance the effectiveness of cancer therapies while safeguarding normal tissues from treatment-induced damage." (PMID 40072085, 2025). "GSK3β influences cancer cell proliferation largely through its modulation of oncogenic pathways, most notably the Wnt/β-catenin signaling pathway, wherein it phosphorylates β-catenin, resulting in its proteasomal degradation and subsequent inhibition of cell proliferation." (PMID 41153674, 2025). "Inhibiting GSK3β could sensitize various cancers to chemotherapy and radiotherapy by disturbing DNA damage repair." (PMID 39762409, 2025). "Additionally, previous studies have reported that GSK3β inhibits EMT to reduce cancer cell metastasis and progression that related to our study." (PMID 40506749, 2025). "Investigating the potential of GSK3β inhibitors to enhance the efficacy of ICIs could lead to improved outcomes for patients with various cancers." (PMID 41190025, 2025). "Researchers have explored the inhibition of GSK-3β as a potential treatment for cancer." (PMID 41039321, 2025). "In addition, multiple investigations have documented elevated levels of the inactive p-GSK3β form in several cancer types." (PMID 41153674, 2025). "Additionally, Mucin 15 (MUC15), which is downregulated in PCa, represents a potential therapeutic target by inhibiting EMT and cancer stemness through the GSK3β/β-catenin signaling pathway." (PMID 40556678, 2025). "We hypothesize that GSK3β, a multifunctional kinase involved in cancer progression and cancers resistant to radio-, chemo- and targeted therapy, might play a role in the anti-cancer-specific function of IL-24." (PMID 40072085, 2025). "This evidence strongly validates that GSK3B is an significant target in cancer therapy." (PMID 39820173, 2025). "Targeting GSK3β in combination with existing cancer therapies may enhance treatment responses and overcome resistance mechanisms." (PMID 41190025, 2025). "For example, studies have shown that GSK3β inhibition can sensitize cancer cells to chemotherapeutic agents, suggesting that this approach could be beneficial in clinical settings." (PMID 41190025, 2025). "Abnormal GSK3B expression and action contribute to the progression of many types of cancer." (PMID 39820173, 2025). "Furthermore, PI3K/AKT/GSK3B is aberrant in a wide range of cancers and has been shown to play a key role in cancer cell proliferation, migration, invasion and apoptosis." (PMID 40071097, 2025). "This duality complicates the development of GSK3β inhibitors as cancer therapies." (PMID 41190025, 2025). "GSK3β inhibition disrupts average glucose utilization in cancer cells, potentially creating metabolic stress that could be exploited therapeutically." (PMID 40072085, 2025). "Similarly, exosomal miR-1290 derived from CAFs facilitates cancer cell proliferation and metastasis through the suppression of the GSK3β/β-catenin pathway." (PMID 40556678, 2025). "Previous studies have mostly demonstrated the regulatory function of GSK3β on glycolysis in cancer." (PMID 40014184, 2025). "Additionally, targeting GSK-3β offers a promising approach to overcoming drug resistance in cancer therapy." (PMID 41217667, 2025).
cancer (continued). "This suggests that targeting both GSK3β and autophagy could provide a dual benefit in cancer treatment." (PMID 41190025, 2025). "Inhibiting GSK3B was shown to abolish 53BP1-mediated IR-induced DNA repair in cancer cells." (PMID 41243969, 2025). "Therefore, we cannot exclude the potential for unintended pro-tumorigenic effects resulting from ArcA-mediated dephosphorylation of GSK-3β at Ser9 in different cancer types." (PMID 39948552, 2025). "Furthermore, targeting GSK-3β presents a promising strategy to overcome drug resistance in cancer treatment." (PMID 41217667, 2025). "Notably, recognizing GSK3β inhibition as a crucial mechanism driving IL-24-mediated cancer-specific apoptosis greatly enhances its therapeutic potential in oncology." (PMID 40072085, 2025). "Inhibiting GSK-3β has shown promise in cancer therapy, including HCC." (PMID 39156976, 2024). "Our previous studies have shown that MYH9 attenuated the GSK3β-mediated ubiquitination and degradation of β-catenin, thereby facilitating Wnt signaling activity and promoting proliferation, metastasis, and chemoresistance of cancer cells." (PMID 38698330, 2024). "When GSK3β is abnormally regulated, it can lead to excessive cell growth, commonly seen in cancer." (PMID 38474160, 2024). "Activation of the proto-oncogenic molecule β-catenin by inhibition of GSK-3 is another major concern claiming that long-term inhibition of GSK-3β may promote cancer." (PMID 38367137, 2024). "Cellular and tissue analyses consistently demonstrate the abundant expression of GSK-3β in these cancers, underscoring its potential as a key target in cancer therapy (R, 2010), This shows that GSK-3β is significantly related to the occurrence and development of these tumors." (PMID 39156976, 2024). "The PI3K/AKT pathway, which is often hyperactive in cancer, negatively regulates GSK3β." (PMID 38474160, 2024). "Furthermore, NMI inhibits AKT and GSK3β/β-catenin signaling in various cancers, thereby impeding cancer progression." (PMID 39125716, 2024). "For example, copper chelation downregulates transcriptomic expression of EMT markers and transcription factors in cancer cell lines, or copper chelation therapy inhibited GSK3B phosphorylation and in turn induced downregulation of PD-L1 and increased anti-cancer immune response." (PMID 38642129, 2024). "However, targeting GSK3β is complex due to its diverse roles in different cancer types and its involvement in multiple signaling pathways." (PMID 38474160, 2024). "In addition, non-selective COX inhibitor ibuprofen also has a chemo-preventive efficacy against cancer by inhibiting GSK-3β and modulating Wnt/β-catenin signaling." (PMID 38367137, 2024). "This analysis indicates that SY may inhibit FGFR2, EGFR, CAH2, KEAP1, and GSK3β, which are involved in various cellular processes related to cancer development and oxidative stress response." (PMID 38431714, 2024). "Alcohol is a known risk factor for CRC, and, in this context, it may accelerate cancer progression by modulating the GSK3β/β-catenin pathway, further promoting tumorigenesis and advancing CRC development." (PMID 39766795, 2024). "As well, naproxen has an anti-cancer effect via inhibition of GSK-3β." (PMID 38367137, 2024). "GSK-3β is critically significant in both the initiation and progression of tumors, playing a pivotal role in the expansion, reproduction, spread, and programmed cell death of cancer cells." (PMID 39156976, 2024). "The finding that GSK3β regulates programmed death ligand-1 (PD-L1) suggests that GSK3β inhibition may be effective in immunotherapy against cancers." (PMID 36672256, 2023). "It was found that SnEA and pyrogallol could inhibit CRPC cell proliferation and promote cancer cell apoptosis via the regulation of the Akt/GSK-3β/β-catenin signaling pathway." (PMID 37047425, 2023).
cancer (continued). "In particular, the use of small-molecule inhibitors of GSK3β in cancer immunotherapy may represent a valuable alternative to antibody-based immune checkpoint blockade (ICB) therapies." (PMID 38139062, 2023). "Furthermore, activation of the AKT/mTOR pathway is known to play a profound role in cancer progression, and GSK-3β itself is involved in this pathway." (PMID 37754254, 2023). "In addition, hirsutine promotes the dephosphorylation of GSK3β the depletion of ATP and facilitates mPTP-mediated cell apoptosis in cancer cells." (PMID 36982637, 2023). "GSK3β has been considered a potential target for therapeutic intervention in cancer." (PMID 37373005, 2023). "Although GSK3β is involved in multiple pathways linked to the etiology of various cancers, no specific GSK3β inhibitor has been authorized for cancer therapy." (PMID 37284581, 2023). "GSK-3β inhibitors were proven to induce autophagy in other cancer types." (PMID 37366889, 2023). "Notwithstanding, GSK-3β is believed to have pro-cancer functions in other literature." (PMID 37129745, 2023). "Predicated on prior studies, we conjectured that Salvigenin might exert an anti-cancer function in HCC mainly via the PI3K/AKT/GSK-3β signaling pathway." (PMID 37129745, 2023). "Through computational simulation, we identified miR-26a bound to the 3′UTR of GSK3β/MYC/CCND1, thus suggesting a close association of Met/GSK3β/MYC/CCND1 and miR-26a promoting cancer proliferation, invasion, migration, drug resistance, and stemness metastasis in CRC patients." (PMID 36672275, 2023). "These discoveries established that Salvigenin might exert an anti-cancer function in HCC primarily by suppressing the PI3K/AKT/GSK-3β pathway." (PMID 37129745, 2023). "GSK-3β can also promote cell proliferation in diverse types of cancers." (PMID 37009796, 2023). "Other studies indicated that TNS4 could promote cancer progression by regulating the Akt/GSK-3b and TGF-b1 signaling pathways." (PMID 37510408, 2023). "Modulation and alteration in GSK3β activity have been investigated in different kinds of cancers." (PMID 36982637, 2023). "This suggests the inhibition of GSK-3β could effectively inhibit cancer cell invasion through regulation of CAP1." (PMID 36430630, 2022). "Interestingly, it has been previously reported that STYK1 can act as a scaffold to enhance the phosphorylation of GSK3β through activated Akt, which likely promotes cancer cell survival." (PMID 35840561, 2022). "Indeed, many reviews showed detailed roles of GSK-3β in cancer and suggested it as an anti-cancer protein." (PMID 36430630, 2022). "In addition, cell localization of GSK-3β seems to play an important role in cancer development and promotion." (PMID 36430630, 2022). "Moreover, GSK-3β has also been found to exhibit carcinogenic properties, as it up-regulates pathways critical for cancer cell survival and drug resistance." (PMID 35847921, 2022). "Therefore, GSK3β has been suggested as a potential drug target for cancer stem cells and immunological/neurological disorders." (PMID 35744952, 2022). "Although the role of GSK3β in cancer has been extensively studied, it still remains controversial." (PMID 35350242, 2022). "Therefore, in this case, inhibition of GSK-3β will lead to activation of β-catenin and its pro-cancer activated pathway leading to cancer promotion." (PMID 36430630, 2022). "Furthermore, five compounds in Qinghao-Kushen targeted GSK-3β, which was involved in the process of multiple cancer pathways." (PMID 35722140, 2022). "GSK3α and GSK3β had specific roles in cell survival, and GSK3α might paly a more important role in cancer cell survival and cancer treatment resistance." (PMID 35292059, 2022). "Interestingly, cells with MST4 overexpression showed an increase in phosphorylation of MST4 substrate protein Ezrin, a protein activating cancer cell invasion, and GSK3β, a protein regulating EMT progression." (PMID 36552828, 2022).
cancer (continued). "Previous studies found that the AKT/GSK‐3β pathway is abnormally expressed in different cancers." (PMID 35567291, 2022). "The table also includes a list of ongoing clinical trials testing GSK-3β inhibitors in cancers." (PMID 36430630, 2022). "Furthermore, pharmacological and molecular inhibitions of GSK-3β reduced the migration ability of cancer cells." (PMID 36430630, 2022). "Therefore, increasing GSK-3β expression by induction of Ras-driven MAPK results in increased cancer cell plasticity and increased EMT." (PMID 36430630, 2022). "However, further studies are required to elucidate the mechanisms underlying Fe2+-mediated Ser 9 phosphorylation and inactivation of GSK3β in cancer cells." (PMID 35986274, 2022). "Therefore, GSK-3β regulates a number of intracellular signaling pathways and is involved in a variety of biological events, including autophagy, cell apoptosis, and cancer progression." (PMID 35847921, 2022). "Based on this data, we can state that the GSK-3β/β-catenin pathway is a pro-cancer pathway in PDAC." (PMID 36430630, 2022). "In addition, CaMKII has been implicated in the activation of multiple oncogenic signaling pathways, such as the MAPK, AKT/mTOR, JAK/STAT, GSK3β/β-catenin, Notch, and NF-κB pathways, which play a critical role in cancer progression." (PMID 35267623, 2022). "In addition to the GSK-3β up-regulation of the NF-κB pathway, which has a broad pro-cancer effect, GSK-3β is also involved in another major pro-cancer pathway in PDAC, namely the k-ras pathway, which is activated in 95% of PDAC patients." (PMID 36430630, 2022). "Moreover, the key roles of GSK-3β in DNA repair, apoptosis, and cancer treatment make it a reliable therapeutic target." (PMID 34485505, 2021). "KRT19 (AUC = 0.855, CI = 0.825 - 0.885) and FKBP10 (AUC = 0.836, CI = 0.808 - 0.864) had a certain accuracy in predicting cancer and normal, and the predictive abilities of GSK3B (AUC = 0.654, CI = 0.613 - 0.696) and SPANXB1 (AUC = 0.682, CI = 0.650 - 0.714) were less accurate." (PMID 35096583, 2021). "GSK-3β is described to be a positive regulator of NF-κB–mediated chemoresistance of cancer cells." (PMID 34955846, 2021). "However, higher ETS1 and GSK3β were expressed in IOSE-80PC cells, suggesting that phosphorylation of ETS1 is mediated via GSK3β thereby activates MMP9 expression in cancer cells." (PMID 34023818, 2021). "In inflammation and cancer, targeting of GSK3β could restore a normal interaction of stem cells with their microenvironment and consequently homeostatic tissue regeneration." (PMID 33498808, 2021). "GSK-3β plays pivotal roles in the pathogenesis of several diseases, including cancer." (PMID 34681807, 2021). "In-silico molecular docking study was also investigated on one of the prominent cancer target receptors, i.e., glycogen synthase kinase-3β (GSK-3β), revealing a good binding interaction with our potent compound, 4k and was in agreement with the in vitro cytotoxic results." (PMID 33503871, 2021). "Thus, the dominant regulation of the activating ligands by GSK-3α, as shown here, highlights the differential roles of GSK-3α and GSK-3β in cancer surveillance by NK cells, further supporting the notion of isoform-specific functions of GSK-3." (PMID 33918810, 2021). "Taken together, our study not only highlights the novel function of CP formula in suppressing metastasis of HBV-associated HCC, but it also addresses the critical role of Cav-1 in mediating Akt/GSK3β/β-catenin axis to control the late-phase of cancer progression." (PMID 34168559, 2021).